CST3 (cystatin C)
Diseases named in the same sentence as CST3 in open-access papers (continued):
Sharing a sentence is not in itself a finding about the gene and the disease.
breast cancer (continued). "Recent studies have shown that CST3 expression negatively correlates with cancer development in breast cancer, CRC, bladder cancer, and hepatocellular carcinoma." (PMID 37445705, 2023). "A dose‐dependent decrease in viable cells was seen for A375 melanoma, MCF‐7 breast cancer, and PC‐3 prostate cancer cells cultured in 1–5 μm cystatin C after 24 h." (PMID 33837649, 2021). "We provide proof-of-principle analysis showing that one of these novel targets, Cystatin C (CST3) is a functionally relevant CIRBP target in breast cancer, as depletion of CST3 abrogates the deleterious effects of CIRBP depletion." (PMID 33172965, 2021). "Among them, we identify CST3 as a functionally relevant target that is down-regulated by CIRBP to promote the tumorigenic properties of breast cancer cells." (PMID 33172965, 2021). "Our data provide a resource of CIRBP targets in breast cancer, and identify CST3 as a novel downstream mediator of CIRBP function." (PMID 33172965, 2021). "Elevated blood levels of cystatin-C have been detected in women with breast cancer and are shown to correlate with cancer progression." (PMID 32344635, 2020). "In order to clarify the effects of autophagy by SAHA and Cystatin C in breast cancer cells, we determined LC3II by fluorescence microscopy." (PMID 28881816, 2017). "In order to investigate the effects of SAHA and Cystatin C on breast cancer cell proliferation, we determined the cell viability and apoptosis in MDA-MB-231 and MCF-7 cell lines." (PMID 28881816, 2017). "The data demonstrated that the depletion of cystatin C in the PyMT breast cancer model reduced tumor growth and proliferation, suggesting a novel function for cystatin C in cancer development and progression." (PMID 29088746, 2017). "We investigated the role of cystatin C in mammary cancer using CstC knockout mice and a mouse model of breast cancer induced by expression of the polyoma middle T oncoprotein (PyMT) in the mammary epithelium." (PMID 29088746, 2017). "In the present study, we evaluated the impact of the depletion of the extracellular cysteine cathepsin inhibitor cystatin C on the development and progression of breast cancer using a PyMT mammary tumor model." (PMID 29088746, 2017). "When matched with patient initial diagnoses, two out of the top three breast cancer patients with the lowest predicted cystatin C levels were those with invasive lobular carcinoma." (PMID 26349896, 2015). "The weighted coefficient matrix calculated from the trained model was used to predict invasion and cystatin C responses of the monocytes from the breast cancer patients if they were differentiated into monocyte-derived macrophages over the 12 day period." (PMID 26349896, 2015). "Human cystatin C has been shown to inhibit epithelial-mesenchymal transition of mammary tumor cells via antagonized binding to the TGF-β receptors on these tumor cells." (PMID 21253577, 2011). "For example, the protein encoded by CST3 is an antagonist of TGF-β signaling and has been shown to be significantly down regulated in many breast cancers." (PMID 20003408, 2009). "Decreased cystatin C mRNA expression has been reported in several types of solid tumors including breast cancer, colon cancer and renal carcinoma." (PMID 19956729, 2009). "This study was designed to explore the relationship between the creatinine-to-cystatin C ratio (CCR) and 1-year all-cause mortality in breast cancer patients, while evaluating the clinical validity of CCR as an independent serological prognostic marker for 1-year mortality risk." (PMID 41383336, 2025). "A breast cancer scRNA‐seq found CST3 overexpression in metastatic non‐TNBC cells." (PMID 38520221, 2024). "In addition, recent studies have shown that cathepsin D can cleave CST3 under an acidic pH, leading to decreased CST3 expression in the breast cancer microenvironment." (PMID 37445705, 2023). "Cystatin C significantly inhibited SAHA-induced CTSB expression in breast cancer cells." (PMID 37576397, 2023).
breast cancer (continued). "The malignant progression of the cancerous cells and tumour formation is exacerbated by reduced levels of the endogenous inhibitors used to regulate the cathepsin peptidases, such as cystatin C that regulates cathepsin B in cases of tongue cancer and breast cancer." (PMID 35214614, 2022). "We could not find any evidence of associations of genetically predicted serum creatinine, enzymatic creatinine, cystatin C, microalbumin, phosphate, potassium, sodium, and total protein with breast cancer liability." (PMID 36424572, 2022). "Although research on cystatin C and breast cancer is limited, prospective studies suggest leptin might be a marker of breast cancer risk." (PMID 31848323, 2019). "Our results reinforce the potential relevance of CD44 as a potential marker of breast cancer as well as propose other proteins that might play key roles as biomarkers such as CST3, which needs to be extensively and individually studied in the serum of large series of patients." (PMID 33224883, 2020). "Whether ranked by cystatin C levels or invasion index, breast cancer patients (BCP) 5, 6, 7, and 8 are consistently scored higher than the others, and their initial cancer diagnoses were invasive lobular, bilateral-invasive lobular, and intraductal carcinomas (IDC)." (PMID 26349896, 2015). "The serum creatinine-to-cystatin C ratio (CCR) is a potential muscle mass biomarker, but its prognostic value in advanced breast cancer is unclear." (PMID 41383336, 2025). "Cystatin-C (CST3) and Xaa-Pro dipeptidase (PEPD) were highly expressed in colon cancer samples compared to breast cancer." (PMID 41516087, 2025). "This study enrolled a total of 465 patients with stage III-IV breast cancer, with a median age of 52.0 (interquartile range [IQR], 47.0–60.0)years and a median creatinine-cystatin C ratio (CCR) of 1.0 (IQR, 0.8–1.2)." (PMID 41383336, 2025). "On the other hand, the oncogenic effect of cystatin C was shown in null mice after injection with metastatic B16F10 melanoma cells and in an orthotopic model of breast cancer, where the depletion of cystatin C resulted in decreased growth of the tumor." (PMID 31340550, 2019). "Cystatin C, a protease inhibitor, significantly inhibited the expression of CTSB induced by SAHA on breast cancer cells." (PMID 28881816, 2017). "We confirmed that Cystatin C, a protease inhibitor, significantly inhibited the expression of CTSB induced by SAHA on breast cancer cells." (PMID 28881816, 2017). "Cystatin C alone had minimal effects on the MDA-MB-231 and MCF-7 cells; however, the combination of Cystatin C and SAHA significantly reversed the inhibitory effect of SAHA on the growth of breast cancer cells." (PMID 28881816, 2017). "Therefore, it may be that an important contribution to the variability in breast cancer cell invasion and tumor growth and spread may be due to the TAMs that infiltrate, and locally secrete cathepsins and cystatin C that can directly assist cancer cell invasion." (PMID 26349896, 2015). "Blood creatinine increased had been observed in patients with breast cancer treated with CDK4/6 inhibitors, and cystatin C may be added for renal function assessment to facilitate subsequent treatment formulation." (PMID 39640578, 2024). "A combination of the independently-associated markers showed a moderately strong association with the risks of cancer and CVD (HRQ4-Q1 ranged from 1.78[1.36, 2.34] for breast cancer, when combining NT-proBNP and HbA1C, to 2.87[2.15, 3.83] for MI when combining NT-proBNP, HbA1C, CRP and cystatin-C)." (PMID 34935094, 2022). "CST3 expression was reported to be upregulated after DNA damage in TNBC cell lines, and showed a positive correlation with trastuzumab resistance in HER-2-positive breast cancers." (PMID 34611125, 2021). "Cystatin C, a CTSB inhibitor (CBi), was also detected in breast cancer cells and its interaction with CTSB may play an important role in breast cancer invasion and metastasis." (PMID 28881816, 2017).
dementia (26 papers, 2010 to 2026). Loss of intellectual abilities interfering with an individual's social and occupational functions. "Cystatin C has a neuroprotective role and low levels of cystatin C in the CSF correlate with rapid dementia progression, suggesting an association with AD." (PMID 39273520, 2024). "Due to the rising prevalence of CKD, it is essential to conduct early screening and risk assessment for dementia in individuals with impaired kidney function, particularly those with significantly elevated levels of cystatin C." (PMID 39412044, 2024). "Overall, elevated cystatin C was associated with dementia (prevalence ratio [PR] = 1.2; 95% CI: 1.0, 1.5)." (PMID 37323925, 2023). "The association between high cystatin C and dementia was suggestive of super-additivity for minoritized racial groups, but the confidence intervals for the additive measures of interaction were imprecise." (PMID 37323925, 2023). "In this large and diverse cross-sectional analysis of older adults in the United States, high levels of serum cystatin C (>1.24 mg/L) were associated with elevated prevalence of cognitive impairment non-dementia and dementia relative to normal cognition." (PMID 37323925, 2023). "In conclusion, we observed that elevated serum cystatin C was associated with 1.2 times higher prevalence of dementia in a large, diverse sample of middle-aged and older US adults." (PMID 37323925, 2023). "Recently, it has been shown that cystatin C was associated with cognitive performance, brain imaging pathology and decline to dementia in 90+-year-olds with a mean eGFR of 39ml/min/1.73 m2." (PMID 35025758, 2022). "The association of serum cystatin C with risk of mild cognitive impairment (MCI) or dementia was inconsistent." (PMID 35153722, 2021). "Second, quantifying the mediating effect of cystatin C on the relationships between race/ethnicity and dementia may identify biological pathways underlying racial and ethnic disparities in cognition." (PMID 37323925, 2023). "Additionally, there have been reports suggesting an association between the levels of Cystatin C in the blood and the risk of developing dementia, as well as cognitive impairment." (PMID 37207178, 2023). "Our findings add to the increasing body of epidemiological evidence linking elevated circulating levels of cystatin C to adverse cognitive aging, elucidating potential shared biological mechanisms implicated in early stages of renal disease and vascular forms of dementia." (PMID 37323925, 2023). "Among the proteins, APOE, CLU, CHL1, SLC1A3, RAB7A, and CST3 were related to the protein aggregation of misfolded proteins—causative agents and symptomatic of neurodegenerative diseases—such as α-synuclein in PD, and amyloid-β and tau in dementia." (PMID 36797805, 2023). "Cystatin C may be relevant to the risk of dementia in PD or be able to reflect treatment response in PDD." (PMID 37569491, 2023). "Elevated cystatin C was associated with dementia prevalence." (PMID 37323925, 2023). "Furthermore, we identified that non-Hispanic Black and Hispanic individuals with high levels of cystatin C are at increased risk for dementia." (PMID 37323925, 2023). "In this study we are aiming to examine the levels of serum cystatin C in AD patients and compare to those in matched healthy subjects, and trying to determine whether serum cystatin C levels are associated with the severity of the dementia." (PMID 35153722, 2021). "Besides, studies have shown that the Cystatin C concentration is also associated with the risk of dementia." (PMID 33243163, 2020). "In addition, low levels of BDNF correlate with the degree of cognitive decline and low levels of cystatin C are associated with an anticipation of dementia onset." (PMID 29249935, 2017). "In dementias the loss of cystatin C may also result in a loss of neuroprotection mediated by autophagy." (PMID 29249935, 2017).
dementia (continued). "Additionally, to follow up on these biomarker candidates, their ability to discriminate AD from other causes of dementia needs to be examined; indeed, several of these markers have already shown promise for distinguishing AD from frontotemporal lobar degeneration (cystatin C, eotaxin-3, and HGF)." (PMID 21526197, 2011). "In our overall sample, model 4 showed that those with high cystatin C had 1.2 (95% CI: 1.0, 1.5) times higher prevalence of dementia and 1.1 (95% CI: 1.0, 1.3) times higher prevalence of CIND than those with low cystatin C levels." (PMID 37323925, 2023). "Among those with cystatin C levels >1.24 mg/L, the prevalence of dementia was 8.7%, and among those with levels <0.86 mg/L was 1.9%." (PMID 37323925, 2023). "Recent research has explored the relationship between Cystatin C levels and cognitive health, with some studies indicating that elevated levels of Cystatin C in the cerebrospinal fluid (CSF) may be linked to a higher likelihood of cognitive decline and dementia in older adults." (PMID 37207178, 2023). "Measures of interaction in the additive scale of the joint effect of race/ethnicity and high cystatin C (>1.24 mg/L) on dementia." (PMID 37323925, 2023). "Adjusted prevalence ratios between high cystatin C levels (>1.24 mg/L) and dementia, and cognitive impairment non-dementia in the United States health and retirement study stratified by race/ethnicity, waves 2006 and 2008." (PMID 37323925, 2023). "Elevated cystatin C was estimated to account for 2% (95% CI: −0, 4%) for the racial disparity in prevalent dementia, and the interaction accounted for 8% (95% CI: −5, 22%)." (PMID 37323925, 2023). "Plasma cystatin C was also indicated to modulate the clinical expression of cognitive decline; a significant anticipation of the conversion to dementia was observed in MCI subjects, when the detected plasma cystatin C levels were below 1,067 ng/ml." (PMID 35153722, 2021). "Unfortunately, there were inadequate numbers of bulbar-, trunk-, and/or dementia-onset patients to analyze these individual subgroups in this study, and further analyses are required to determine the prognostic capacity of cystatin C in these subgroups." (PMID 21151566, 2010). "Plasma Cystatin C levels were significantly correlated with dementia." (PMID 39050669, 2024). "In conclusion, these findings suggest that calculating renal function based on serum cystatin C levels may be an early indicator of dementia." (PMID 39412044, 2024). "The association between high cystatin C and dementia—but not cognitive impairment non-dementia—was similar across all racial groups." (PMID 37323925, 2023). "Third, estimating the proportion of racial and ethnic disparities in dementia that could be reduced if cystatin C was amenable to intervention is useful to inform public health efforts and policies." (PMID 37323925, 2023). "But the association between elevated cystatin C and dementia was null for non-Hispanic White adults when APOE-ε4 was added to the model." (PMID 37323925, 2023). "Prevalence ratios estimates from Poisson regression models illustrating the association between the joint effect of race/ethnicity and high cystatin C serum levels (>1.24 mg/L) and dementia or cognitively impaired non-dementia in the health and retirement study, waves 2006 and 2008." (PMID 37323925, 2023). "Our analysis builds on these findings, by suggesting that the effect of cystatin C on dementia differs based on whether older adults are racialized as non-Hispanic Black or Hispanic rather than non-Hispanic White." (PMID 37323925, 2023). "Elevated circulating cystatin C is associated with cognitive impairment in non-Hispanic Whites, but its role in racial disparities in dementia is understudied." (PMID 37323925, 2023).
dementia (continued). "But at least two case-control studies have explored the relationship between CST3 polymorphism and APOE-ε4 allele in Alzheimer’s patients of European ancestry, one concluding a synergistic association between APOE-ε4 allele and CST3 polymorphism on dementia risk." (PMID 37323925, 2023). "The effect of cystatin C on prevalent dementia may be moderated by race/ethnicity, indicating that racialization affects not only the distribution of serum cystatin C across minoritized racial groups, but also the strength of association between the biomarker and dementia." (PMID 37323925, 2023). "Our interaction results suggest that when comparing Hispanic to non-Hispanic White participants, the association between elevated cystatin C on prevalent dementia was of lesser magnitude than when comparing the non-Hispanic Black participants to their non-Hispanic White counterparts." (PMID 37323925, 2023). "In addition, two baselines from the Atherosclerosis Risk in Communities (ARIC) Study, including 9967 participants aged 54 to 74 years, showed that lower estimated glomerular filtration rate (eGFR) based on cystatin C or β2-microglobulin, but not creatinine was associated with dementia." (PMID 37190655, 2023). "Model 4 showed non-Hispanic Black participants with high cystatin C levels (double exposed group) had 5.8 (95% CI: 4.3, 7.9) times the prevalence of dementia than non-Hispanic White participants with low cystatin C (unexposed group)." (PMID 37323925, 2023). "In multivariable-adjusted models, we found that the double exposed group (non-Hispanic Black participants with high cystatin C) had higher prevalence of dementia than the unexposed group (non-Hispanic White participants with low cystatin C)." (PMID 37323925, 2023). "Model 4 showed that Hispanic participants with high cystatin C levels (double exposed group) had 5.0 (95% CI: 3.3, 7.5) times the prevalence of dementia than non-Hispanic White participants with low cystatin C (unexposed group)." (PMID 37323925, 2023). "The use of Power’s algorithm for dementia classification dramatically attenuated the point estimates for our double exposed subgroups (non-Hispanic Black and Hispanic participants with high cystatin C) and hence their measures of additive interaction." (PMID 37323925, 2023). "We also found strong non-linear association of creatinine (P for non-linearity = 0.009), cystatin C (P for non-linearity = 0.028), urate (P for non-linearity = 0.007) and urea (P for non-linearity = 5.0E-09) with dementia." (PMID 35927253, 2022). "The one-way ANOVA analyses showed that the serum cystatin C levels were not significantly different among AD patients with different severities of dementia (p = 0.6588)." (PMID 35153722, 2021). "In the demographic-adjusted model, among non-Hispanic Black participants with high cystatin C (double exposed group), the prevalence of dementia was 2.6 (95% CI: 2.0, 3.3) times higher than for non-Hispanic White participants with low cystatin C (unexposed group)." (PMID 37323925, 2023).